CETN3 (centrin 3)
Description:
Plays a fundamental role in microtubule-organizing center structure and function. As a component of the TREX-2 complex, involved in the export of mRNAs to the cytoplasm through the nuclear pores.
Synonyms: CEN3; CDC31
Tractability: PROTAC: ubiquitination databases record sites on it; its protein half-life has been measured.
Gene: Protein-coding gene on chromosome 5 (90,392,257 to 90,409,786, reverse strand). Ensembl gene ENSG00000153140.
Subcellular location: Cytoplasm, cytoskeleton, microtubule organizing center, centrosome; Nucleus, nucleolus; Nucleus envelope; Nucleus, nuclear pore complex; Cytoplasm, cytoskeleton, microtubule organizing center, centrosome, centriole
Subcellular location (Human Protein Atlas): Centrosome; Basal body
Gene Ontology:
Molecular function: protein binding; microtubule binding; calcium ion binding; G-protein beta/gamma-subunit complex binding
Biological process: centrosome cycle; microtubule cytoskeleton organization; mRNA export from nucleus; positive regulation of transcription by RNA polymerase II
Cellular component: centriole; centrosome; nuclear envelope; nuclear pore nuclear basket; transcription export complex 2; microtubule organizing center; ciliary basal body; ciliary transition zone; nuclear pore; nucleolus; photoreceptor connecting cilium
Genetic constraint (gnomAD): Loss-of-function variants: 8 observed, 7.73 expected, observed/expected ratio (o/e) 1.03, 90% interval 0.6 to 1.75. That is too few expected variants to judge how well the gene tolerates losing a copy. Missense variants: 72 observed, 89.25 expected, observed/expected ratio (o/e) 0.81, 90% interval 0.67 to 0.98. Synonymous variants: 22 observed, 27.94 expected, observed/expected ratio (o/e) 0.79, 90% interval 0.56 to 1.12.
Homologues: Orthologues: chimpanzee CETN3 (100% identical), macaque CETN3 (100% identical), mouse Cetn3 (99% identical), rabbit CETN3 (97% identical), rat Cetn3 (96% identical), dog CETN3 (92% identical), guinea pig CETN3 (92% identical), pig CETN3 (92% identical), zebrafish cetn3 (84% identical), Caenorhabditis elegans cal-3 (32% identical), Caenorhabditis elegans cal-1 (31% identical), Caenorhabditis elegans B0563.7 (29% identical), and 5 more. Paralogues in human: CETN2 (54% identical), CETN1 (53% identical), CALM1 (36% identical), CALM2 (36% identical), CALM3 (36% identical), CALML3 (35% identical), CABP4 (32% identical), CABP2 (32% identical), CALML6 (31% identical), CALML5 (30% identical), CABP1 (29% identical), CABP5 (27% identical), and 8 more.
Diseases named in the same sentence as CETN3 in open-access papers:
CETN3 is named in the same sentence as 11 diseases in open-access papers, as found by Europe PMC text mining. Sharing a sentence is not in itself a finding about the gene and the disease. The quoted sentences say what the papers report.
colorectal cancer (1 paper, 2023). A primary or metastatic malignant neoplasm that affects the colon or rectum. "In conclusion, the increment of SLMAP exon 24 inclusion and CETN3 exon 5 exclusion were observed in human colorectal cancer and predicted as potential targets for CRC patients." (PMID 36623729, 2023).
glioma (1 paper, 2010). A benign or malignant brain and spinal cord tumor that arises from glial cells (astrocytes, oligodendrocytes, ependymal cells). "Comparing with normal human brain tissue, most of the mRNAs expression in gliomas for centrosomal structural proteins, including centrin 3, γ-tubulin, and hNinein isoforms 1, 2, 5 and 6, Aurora A and Aurora B were elevated." (PMID 20529377, 2010).
microcephaly (1 paper, 2025). A congenital or acquired developmental disorder in which the circumference of the head is smaller than normal for the person's age and sex. "Through whole-exome sequencing, we identified compound heterozygous loss-of-function mutations in CENTRIN 3 (CETN3) in a 5-year-old patient with primary microcephaly." (PMID 40926052, 2025). "We showed that CETN3-knockout (KO) organoids successfully recapitulated the microcephaly phenotype of reduced size compared to the control organoids." (PMID 40926052, 2025). "As CETN3 has not been previously linked to microcephaly, we investigated its potential function in neurodevelopment in human pluripotent stem cell-derived cerebral organoids." (PMID 40926052, 2025).
retinal degeneration (1 paper, 2025). Degeneration of the retina. "It is worth noting that disruptions in Cetn2 expression solely do not have extensive implications for retinal degeneration due to Cetn3 redundancy." (PMID 40558514, 2025).
retinitis pigmentosa (1 paper, 2022). Retinitis pigmentosa (RP) is an inherited retinal dystrophy leading to progressive loss of the photoreceptors and retinal pigment epithelium and resulting in blindness usually after several decades. "Notably, at the MIR9-2 locus, MEF2C interacts with the gene CETN3 which is associated with retinitis pigmentosa and located over 1 Mb away." (PMID 36207300, 2022).
cancer (4 papers, 2020 to 2023). A tumor composed of atypical neoplastic, often pleomorphic cells that invade other tissues. "Cancer-related splice variants in SLMAP and CETN3 were validated by regulation of SRSF2 at the molecular level." (PMID 36623729, 2023). "SRSF2 regulated cancer-related SLMAP and CETN3 to generate different splice variants with distinct functions in cancer." (PMID 36623729, 2023). "In support of this model, we find that CETN3, MBLAC2, and LYSMD3, core members of the POLR3G promoter hub, feature particularly high correlation z-scores across cancers." (PMID 37894362, 2023). "miR-410 negatively regulates Bcl2 antagonist killer 1 (BAK1), Centrin 3 (CETN3) and Bromodomain containing protein 7 (BRD7) to promote other cancers." (PMID 38201476, 2023). "AIDA, CETN3, FYB1 and POLR2D are also unfavourable prognostic markers across multiple cancer types." (PMID 32635403, 2020).
tumor (3 papers, 2020 to 2023). "In this study, the elevated inclusion of SLMAP exon 24 and reduced inclusion of CETN3 exon 5 were observed in CRC tumor samples." (PMID 36623729, 2023). "Significantly higher transcript levels were observed in GBM tumours for AIDA (2.5-fold, p = 3.4 × 10−8), BNIP3L (1.2-fold, p = 5.5 × 10−6), CETN3 (1.8-fold, p = 1.7 × 10−7), FYB1 (1.8-fold, p = 7.25 × 10−9) and POLR2D (1.7-fold, p = 8.14 × 10−5)." (PMID 32635403, 2020). "Interestingly, AIDA, BNIP3L, CETN3, FYB1 and POLR2D were specific to GBM plasma-EV, and correspondingly, significantly higher gene expression levels were observed in GBM tumour tissue relative to healthy brain." (PMID 32635403, 2020).
CETN3 also shares sentences with these, for which no sentence is quoted: breast carcinoma (1 paper); colon cancer (1); gastric cancer (1); neuromuscular disease (1).